SOD2 (superoxide dismutase 2)
Diseases named in the same sentence as SOD2 in open-access papers (continued):
Sharing a sentence is not in itself a finding about the gene and the disease.
ischemia (32 papers, 2011 to 2025). A hypoperfusion of the BLOOD through an organ or tissue caused by a PATHOLOGIC CONSTRICTION or obstruction of its BLOOD VESSELS, or an absence of BLOOD CIRCULATION. "Expressions of activated caspase-3 and caspase-8, Sod2, and inflammation-related proteins as well as p38 phosphorylation were significantly upregulated in the ischemia-injured rats." (PMID 31379990, 2019). "A study showed that, along with severe ischemic brain damage 3 days after pdMCAO, Nrf2 deficiency destroyed the ischemia-induced increase of antioxidant/detoxification proteins NQO1, HO1, SOD2, and Gpx1." (PMID 30890934, 2019). "In the Tat-PDIA3-treated group, SOD2 activity significantly increased (1.249- and 1.271-fold, respectively) compared with the vehicle-treated group 24 h and 72 h after ischemia/reperfusion, and to the control." (PMID 28981094, 2017). "It was demonstrated that SOD2 overexpression protects mitochondrial respiratory function and blocks apoptosis induction during heart ischaemia reperfusion injury and attenuates mitochondrial ROS generation, intracellular lipid peroxidation and cell death." (PMID 27957793, 2017). "Protective effects of HBOT related to increased production of SOD2 have been demonstrated in the model of ischemia." (PMID 23275324, 2012). "However, in astaxanthin-treated gerbils, the expression of SOD1 and SOD2 was significantly high compared to in-vehicle-treated gerbils before and after ischemia induction." (PMID 35447940, 2022). "Gene expression ratios of the antioxidant enzymes Gpx1, Sod1 and Sod2, Cat and Hmox1 were evaluated 24 hours after ischemia by means of qRT-PCR to determine whether increased antioxidative capacity might be involved in FXN-mediated neuroprotection." (PMID 29555919, 2018). "Similarly, in isolated hearts with ischemia/reperfusion injury, we also found that SOD-2 and thioredoxin were remarkably reduced in the left ventricle of rat hearts subjected to 30 min ischemia followed by 2 h reperfusion (n = 4, P < 0.01 vs. sham group)." (PMID 27819271, 2016). "Additionally, two neuroprotective proteins, heat shock protein 72 (HSP72) and mitochondrial superoxide dismutase 2 (SOD2), have been demonstrated to reduce neuronal damage during ischemia in the forebrain by protecting astrocytes from GLT-1 and reducing oxidative stress." (PMID 38362904, 2024). "Besides, the expression of oxidative stress-related signaling protein Sod2 and the phospho-p38/total p38 ratio was also significantly upregulated in the retina of the ischemia-injured rats by 1.17 and 1.88 folds (p < 0.01), respectively, compared to the uninjured normal rats." (PMID 31379990, 2019). "Resveratrol can reduce intestinal ischemia-reperfusion injury by activating the SIRT3/FoxO3a pathway, increasing the expression of SOD2 and catalase, reducing ROS and LPO production, compensating for the GSH/GPX4 pathway and inhibiting ferroptosis." (PMID 37858064, 2023). "A previous experiment has found that antioxidant enzymes including SOD-1, SOD-2, CAT, and GPx in kidneys exposed to ischemia for 30, 60, 90 min, 2 h, and 24 h are reduced significantly." (PMID 36790289, 2023). "Hypoxic preconditioning has also been proven to upregulate superoxide dismutase 2 (SOD2), making ADSCs more resistant to ROS generated from ischemia and improving retention in vivo." (PMID 36153544, 2022). "The obvious increase of Nrf2 downstream antioxidant proteins can be sustained for at least 3 days following ischemia, revealed by the 1.8- to 3.6-fold increase in HO1, NQO1, SOD2, and GPx proteins after pdMCAO." (PMID 30890934, 2019). "In the HFD/Fucoidan-sham and ischemia groups, SOD1 and SOD2 immunoreactivity was similar to that in the ND-fed group (Figure 8Bi′–Bl′, D and Figure 10Bi′–Bl′, D)." (PMID 30696078, 2019).
ischemia (continued). "In the HFD/Fucoidan-ischemia group, SOD1 and SOD2 immunoreactivity in CA1 pyramidal cells was decreased with time after tGCI, but each immunoreactivity was higher than that in the HFD-ischemia group (Figure 8Aj–Al, C and Figure 10Aj–Al, C)." (PMID 30696078, 2019). "In the HFD-ischemia group, SOD1 and SOD2 immunoreactivity was gradually decreased with time, and, at 5 days after tGCI, SOD1 and SOD2 immunoreactivity was very low due to the damage of CA2/3 pyramidal cells (Figure 8Bf′–Bh′, D and Figure 10Bf′–Bh′, D)." (PMID 30696078, 2019). "Conversely, endogenous protective pathways exist to counteract these detrimental effects induced by ischemia including mitochondria proteins UCP2 and SOD2, which are all regulated by PGC-1α." (PMID 22072942, 2011). "Moreover, the expression of the antioxidant enzymes superoxide dismutase (SOD1 and SOD2) in CA1-3 pyramidal cells were gradually and significantly reduced after ischemia." (PMID 35447940, 2022). "In support of this notion, we found that ANXA1sp significantly increased the protein levels of the antioxidant enzyme superoxide dismutase 2 (SOD2) under both sham and ischemia conditions, indicating that ANXA1sp is able to upregulate protective antioxidant enzymes." (PMID 34276404, 2021). "No significant changes were observed in SOD2 protein levels with exercise nor ischaemia (ANOVA FIO2 effect p = 0.34; time effect p = 0.45, FIO2 by time interaction p = 0.22)." (PMID 32863217, 2020). "In the HFD-ischemia group, SOD1 and SOD2 immunoreactivity in CA1 pyramidal cells was significantly decreased from 1 day after tGCI, and, at 5 days after tGCI, SOD1 and SOD2 immunoreactivity was rarely observed in CA1 pyramidal cells due to their death (Figure 8Af–Ah, C and Figure 10Af–Ah, C)." (PMID 30696078, 2019). "In the ND-ischemia group, SOD1 and SOD2 immunoreactivity in CA1 pyramidal cells was significantly decreased to about 69% and 67%, respectively, of the ND-sham group at 1 day after tGCI, and, at 2 days after tGCI, SOD1 and SOD2 immunoreactivity was more decreased." (PMID 30696078, 2019). "PGC-1α has been shown to be induced after transient global ischemia, where it protects hippocampal neurons from delayed cell death, and knocking down the gene results in lower expression of UCP2 and the antioxidant enzyme superoxide dismutase 2 (SOD2) leading to neuronal death from oxidative stress." (PMID 21910904, 2011).
diabetic nephropathy (31 papers, 2013 to 2026). "Our findings of increased ESRD risk in variant SOD2 Val/Val carriers is aligned with several studies concluding that this polymorphism increases the risk of diabetic nephropathy in both T1DM and T2DM patients." (PMID 31340563, 2019). "In conclusion, we have observed associations of allelic variations of SOD2 gene with the incidence and the progression of diabetic nephropathy, with the decline of eGFR, and with plasma AOPP concentration and SOD activity in subjects with type 1 diabetes." (PMID 24819633, 2014). "We observed associations of SOD2 gene variants with diabetic nephropathy in cohorts of subjects with type 1 diabetes." (PMID 24819633, 2014). "GENESIS and GENEDIAB pooled studies – subset of participants with non-proliferative or pre-proliferative retinopathy: genotype frequencies of SOD2 polymorphisms by stages of diabetic nephropathy." (PMID 24819633, 2014). "SOD2 allelic variations were associated with the incidence and the progression of diabetic nephropathy, with a faster decline in eGFR and with plasma AOPP concentration and SOD activity in subjects with type 1 diabetes." (PMID 24819633, 2014). "Previous investigations reported associations of a missense variant in the exon 2 of the SOD2 gene (rs4880: V16A) with diabetic nephropathy in subjects with type 1 diabetes." (PMID 24819633, 2014). "Furthermore, detrimental polymorphisms in the human SOD2 gene inhibiting processing of this antioxidant enzyme have been shown to be associated in T1D patients exhibiting various complications such as diabetic nephropathy." (PMID 41033431, 2026). "In a diabetic nephropathy model, the administration of mitochondria effectively abolished ROS production by restoring the levels of superoxide dismutase 2 (SOD2) and preventing apoptosis through the upregulation of Bcl-2 protein." (PMID 40741287, 2025). "In the present study, we investigated associations of a set of SOD2 tagSNPs, plasma AOPP concentration and SOD activity with diabetic nephropathy in type 1 diabetic subjects." (PMID 24819633, 2014). "We investigated associations of SOD2 allelic variations, plasma SOD activity and AOPP concentration with diabetic nephropathy in type 1 diabetic subjects." (PMID 24819633, 2014). "Therefore, the role of SOD2 in diabetic nephropathy is controversial, and additional research is needed to determine the mechanisms of SOD2 activity in diabetic nephropathy." (PMID 33477607, 2021). "The polymorphisms in Nrf2, superoxide dismutase (SOD2), and glutathione peroxidase (GPX1) genes, individually, have been implicated previously in disease susceptibility or prognosis in end-stage renal disease (ESRD), CKD, or diabetic nephropathy patients." (PMID 31340563, 2019). "The molecular mechanisms beyond the associations of SOD2 variants with diabetic nephropathy are not fully elucidated." (PMID 24819633, 2014). "Thus, our findings suggest that deletion of SOD2 in the proximal tubular compartment of the kidney induces a more subtle phenotype than expected, shedding light on the involvement of SOD2 and the proximal tubular compartment in the pathogenesis of diabetic kidney disease." (PMID 40127616, 2025).
dilated cardiomyopathy (28 papers, 2006 to 2025). Cardiomyopathy which is characterized by dilation and contractile dysfunction of the left and right ventricles. "It has also been shown that complete SOD2 deficiency in mice was associated with dilated cardiomyopathy and increased neonatal mortality." (PMID 29160855, 2017). "The SOD2 deficiency on a CD1 background resulted in neonatal death by day 10 from severe dilated cardiomyopathy, liver dysfunction, and metabolic acidosis." (PMID 26301039, 2015). "We reported that heart/muscle-specific SOD2-deficient mice (H/M-Sod2−/−) show dilated cardiomyopathy involving the excess generation of ROS by mitochondria." (PMID 26301039, 2015). "In animal models, mice deficient in SOD2 (Sod2-/-) exhibit neonatal lethality in association with dilated cardiomyopathy and a massive lipid accumulation in the liver, while (Sod2+/-) heterozygous mice have increased cancer incidence without affecting aging." (PMID 20003469, 2009). "In addition, SOD2 deficiency in mouse causes dilated cardiomyopathy, the protein levels of SOD2 are markedly decreased in murine hypertrophic hearts and human failing myocardia." (PMID 32424140, 2020). "We previously showed that inhibition of SOD2 expression induced both mitochondrial oxidative stress and cardiomyocytes hypertrophy, and mice deficient in SOD2 in cardiomyocytes have altered defective mitochondrial bioenergetics that cause lethal dilated cardiomyopathy." (PMID 35453408, 2022). "The germline deletion of the Sod2 gene yields very severe phenotypes (dilated cardiomyopathy, hypothermia, growth retardation, and accumulation of lipids in the liver)." (PMID 38892170, 2024). "Further, conventional SOD2 KO mice died in their first weeks of life while developing dilated cardiomyopathy, acidosis, neurodegeneration and progressive motor disturbances." (PMID 37609868, 2023). "Not surprisingly, SOD2 expression is essential for survival, as deletion of the SOD2 gene in mice resulted in death within five days after birth, along with severe dilated cardiomyopathy and accumulated lipid in the liver and muscles." (PMID 27023612, 2016). "When Sod2 was specifically deleted in the heart and muscle, all mice exhibited dilated cardiomyopathy (DCM) and died by six months of age." (PMID 23348992, 2013). "These mice exhibit phenotypes that were typical in Sod2 knockout mice, including elevated levels of oxidative stress in various tissues, fat deposition in liver and muscles, dilated cardiomyopathy, and premature death." (PMID 16450009, 2006). "Furthermore, SOD2 KD in animal models was reported to induce dilated cardiomyopathy by induction of apoptosis." (PMID 41462644, 2025). "In addition, bigenic heterozygous mice generated by crossing the two independent transgenic lines showed phenotypes typical of the SOD2-null mouse, including slow growth, fatty liver, dilated cardiomyopathy, and premature death." (PMID 16450009, 2006). "This substrain of C57BL6/J mice shows an increased sensitivity to O2·−/ H2O2, particularly in the absence of mitochondrial MnSOD (SOD2) and a deficiency in both antioxidants results in death within 1–2 days due to dilated cardiomyopathy." (PMID 24623797, 2014). "We quantified COX5A, COX5B, and SOD2 protein levels in heart samples from patients with end-stage dilated cardiomyopathy (DCM) or subjects without obvious cardiovascular diseases, and observed that COX5A and SOD2 were clearly down-regulated in heart tissues with DCM." (PMID 37373547, 2023). "Lack of SOD2 gene in mouse germ line resulted in much greater and earlier retinal changes including photoreceptor degeneration compared to the SOD1 knockout mice; however, these mice died before weaning due to dilated cardiomyopathy." (PMID 22715395, 2012).
neuroblastoma (28 papers, 2006 to 2025). Neuroblastoma (NB) is the most common solid, extracranial childhood tumor. "The apoptotic effect of diclofenac in neuroblastoma cell lines was suggested to be linked with superoxide dismutase 2 (SOD2)." (PMID 36139546, 2022). "On the other hand, it has been clearly demonstrated that AtRA markedly induces manganese superoxide dismutase (SOD2) activity in human neuroblastoma." (PMID 38227157, 2024). "Borrelia burgdorferi originated-OMVs serve to directly counter superoxide production via SOD2 expression in human neuroblastoma cells." (PMID 34790655, 2021). "In a neuron-like cell model (differentiated mouse neuroblastoma N2a cells), Znf179 was found to protect neurons against ROS by increasing the levels of peroxidase 3 (Prx3) and superoxide dismutase 2 (SOD2)." (PMID 34970121, 2021). "Our results also indicate that the pre-exposure of neuroblastoma cells to RF strongly limited the MD-dependent decrease in both gpx1/sod1 (0.72) and gpx1/sod2 (0.82) ratios." (PMID 30185877, 2018). "Elevated SOD2 expression during differentiation of iPSCs and neuroblastoma cells was discovered in previous studies for sustaining redox homeostasis and preventing ROS-induced cell death." (PMID 27168957, 2016). "Specifically, roxadustat reversed MPTP-induced SH-SY5Y neuroblastoma cell apoptosis, upregulated mitochondrial respiration and counterbalanced oxidative stress by upregulating Nrf-2, heme oxygenase-1 (HO-1) and superoxide dismutase 2 (SOD2)." (PMID 35281917, 2022). "Moreover, the CAT-based antioxidant efficiency was clearly elevated by RF, as we found that the pre-exposure of neuroblastoma cells to RF completely reverted the MD-induced decrease in cat/sod2 ratio (1.33)." (PMID 30185877, 2018). "ATRA induces the expression of both mRNA and protein of the differentiation marker manganese superoxide dismutase (MnSOD) in human neuroblastoma (SK-N-SH) cells with involvement of NF-κB and SOD2 genes, contributing to the concept of using retinoids in cancer therapy." (PMID 21876694, 2012). "The ER marker calnexin was only detectable in total cell homogenates, whereas SOD2, the mitochondrial marker, could be detected in total cell homogenates as well as in the mitochondria fractions of mock-transfected as well as APPswedish transfected human neuroblastoma cells." (PMID 34440266, 2021). "A protective role of TRPM2 under hypoxia can also be found in neuroblastoma cells, in which activated TRPM2 channels lead to increased expression of superoxide dismutase 2 (SOD2) and reduced ROS levels." (PMID 29772843, 2018). "Incubation with H2O2 of SKNBE neuroblastoma cells was also accompanied by PGC-1α and SOD2 induction at both mRNA and protein level, showing that this response is not specific for fibroblasts." (PMID 20383327, 2010). "Primary human retinal pigment epitheliums (hRPE) and human neuroblastoma cells (SH-SY5Y) were transfected with SOD2 or negative control plasmids for 48 h, respectively, before exposure to hydrogen peroxide for 12 h." (PMID 36017189, 2022). "Interestingly, in SKNBE neuroblastoma cells, Pioglitazone incubation for 96 hours at 10 μM increased PGC-1α and SOD2 levels as well as frataxin amount." (PMID 20383327, 2010).